AP1M2 (adaptor related protein complex 1 subunit mu 2)
Description:
Subunit of clathrin-associated adaptor protein complex 1 that plays a role in protein sorting in the trans-Golgi network (TGN) and endosomes. The AP complexes mediate the recruitment of clathrin to membranes and the recognition of sorting signals within the cytosolic tails of transmembrane cargo molecules.
Synonyms: HSMU1B; mu2; AP1-mu2; MU-1B; MU1B
Tractability: Antibody: UniProt places it where antibodies can reach, with medium confidence. PROTAC: ubiquitination databases record sites on it.
Gene: Protein-coding gene on chromosome 19 (10,572,670 to 10,587,315, reverse strand). Ensembl gene ENSG00000129354.
Subcellular location: Golgi apparatus; Cytoplasmic vesicle, clathrin- coated vesicle membrane
Subcellular location (Human Protein Atlas): Vesicles; Cytosol
Pathways (Reactome):
Vesicle-mediated transport: Golgi Associated Vesicle Biogenesis; Lysosome Vesicle Biogenesis
Disease: Nef mediated downregulation of MHC class I complex cell surface expression
Immune System: MHC class II antigen presentation
Gene Ontology:
Molecular function: clathrin adaptor activity; protein binding
Biological process: basolateral protein secretion; Golgi to vacuole transport; vesicle-mediated transport; establishment of localization in cell; establishment of protein localization; intracellular protein transport
Cellular component: AP-1 adaptor complex; cytoplasmic vesicle membrane; cytosol; Golgi membrane; lysosomal membrane; trans-Golgi network membrane; clathrin adaptor complex; clathrin-coated vesicle membrane; Golgi apparatus
Genetic constraint (gnomAD): Loss-of-function variants: 41 observed, 49.59 expected, observed/expected ratio (o/e) 0.83, 90% interval 0.64 to 1.07. The upper end of that interval is the gene's LOEUF score, 1.07, which puts it in group 4 of 6, group 1 being the genes least tolerant of losing a copy. Missense variants: 507 observed, 542.34 expected, observed/expected ratio (o/e) 0.93, 90% interval 0.87 to 1.01. Synonymous variants: 219 observed, 206.57 expected, observed/expected ratio (o/e) 1.06, 90% interval 0.95 to 1.19.
Homologues: Orthologues: chimpanzee AP1M2 (99% identical), macaque AP1M2 (99% identical), pig AP1M2 (97% identical), dog AP1M2 (97% identical), mouse Ap1m2 (97% identical), rat Ap1m2 (97% identical), guinea pig AP1M2 (95% identical), tropical clawed frog ap1m2 (90% identical), zebrafish ap1m2 (83% identical), rabbit AP1M2 (80% identical). Paralogues in human: AP1M1 (79% identical), AP2M1 (40% identical), AP3M1 (31% identical), AP3M2 (30% identical), AP4M1 (30% identical), STON2 (23% identical), STON1 (21% identical).
Diseases named in the same sentence as AP1M2 in open-access papers:
AP1M2 is named in the same sentence as 19 diseases in open-access papers, as found by Europe PMC text mining. Sharing a sentence is not in itself a finding about the gene and the disease. The quoted sentences say what the papers report.
breast carcinoma (5 papers, 2020 to 2024). "In another patient with breast cancer, AP1M2 was below 0.25% in consecutive tests, but the patient achieved OR and her CCF value changed from 1.02 to 0.32%." (PMID 32738923, 2020). "The study revealed a significant upregulation in AP1M2, PSMD10, and RPL2 expression in breast cancer tissue compared to normal tissues." (PMID 38418940, 2024).
invasive breast carcinoma (3 papers, 2022 to 2023). A carcinoma that infiltrates the breast parenchyma. "As AP1M2 was highly and differentially expressed in invasive breast carcinoma, the purpose of this study was to explore the association of AP1M2 gene with the survival, immune invasion, and tumor neoantigens of patients on a pan-cancer basis." (PMID 35154321, 2022). "The findings indicated that the AP1M2 expression level exhibited a positive link to the prognosis and immune aspects of several different tumors, especially breast-infiltrating carcinomas." (PMID 35154321, 2022). "In addition, AP1M2 expression was positively correlated with tumor immune neoantigens and microsatellite instability in invasive breast carcinoma." (PMID 36642706, 2023). "Also, AP1M2 expression was positively correlated with tumor immune neoantigens and microsatellite instability in breast invasive carcinoma." (PMID 35154321, 2022).
hepatocellular carcinoma (2 papers, 2024). A malignant tumor that arises from hepatocytes. "Additionally, TTYH2 and AP1M2 are implicated in cancer progression through regulation of the JNK/ERK Signalling Pathway in Hepatocellular Carcinoma." (PMID 38902676, 2024). "LAPTI, composed of four lysosome‐related genes (CTSV, LAPTM4B, DNAJC6, AP1M2), is a reliable prognostic indicator for hepatocellular carcinoma patients and is validated in external data sets." (PMID 39695350, 2024).
liver cancer (2 papers, 2022 to 2024). An epithelial or non-epithelial malignant neoplasm that arises from the liver. "Upregulation in HBV tumor tissue is consistent with previous studies showing that AP1M2 upregulation by HBV is implicated in the proliferation of liver cancer cells." (PMID 39005337, 2024).
lung carcinoma (2 papers, 2022 to 2026). "A systematic multi-omics analysis was conducted for the eight AP-1 adaptor complex genes (AP1AR, AP1B1, AP1G1, AP1G2, AP1M1, AP1M2, AP1S1, and AP1S3) to characterize their roles in lung cancer." (PMID 41438582, 2026).
pancreatic cancer (2 papers, 2021 to 2023). "A novel 14-gene signature comprising CCDC148, SH3RF2, CACNA1D, POLD3, PARP1, AP1M2, C4orf19, ANO1, VGLL1, SCEL, INPP4B, NET1, INSIG2 and BVES and a corresponding risk score formula were established for pancreatic cancer risk stratification and prognosis prediction." (PMID 33731794, 2021).
prostate carcinoma (2 papers, 2020 to 2022). A carcinoma that arises from epithelial cells of the prostate gland. "Some of the genes associated with these 16 sites included PLEKHA7, AP1M2, ATP9A, and ARVCF known to be downregulated in breast and prostate cancer (data not shown), as well as other cancers." (PMID 32503656, 2020).
acute myeloid leukemia (1 paper, 2022). Acute myeloid leukemia (AML) is a group of neoplasms arising from precursor cells committed to the myeloid cell-line differentiation. "Conversely, some datasets also showed that AP1M2 was poorly expressed in kidney cancer and acute myeloid leukemia compared to normal tissues in the control group." (PMID 35154321, 2022).
bladder cancer (1 paper, 2023). "The observation that low levels of AP1M2 is associated with poor prognosis in bladder cancer patients is, therefore, meaningful." (PMID 36672328, 2023).
Chronic colitis (1 paper, 2020). A chronic inflammatory disease of the large intestine (colon, cecum and rectum). "Deficiency of the AP-1B μ subunit (Ap1m2-/-) leads to the development of chronic colitis in mice." (PMID 32208434, 2020). "Thus, we hypothesize that enhanced iron sequestration by the resident gut bacteria leads to an anemic condition in the KO group having chronic colitis as a result of the Ap1m2-/- gene knockout." (PMID 32208434, 2020). "In addition, the effect of the absence of the Ap1m2 gene on the gut microbes and their potential functions in the development or progression of spontaneous chronic colitis remains unknown." (PMID 32208434, 2020).
clear cell carcinoma (1 paper, 2019). "Interestingly, AP1M2 was highly upregulated exclusively in clear cell carcinoma compared to normal tissue." (PMID 31159852, 2019).
colitis (1 paper, 2020). Inflammation of the colon. "To gain insights into the gut microbiome of Ap1m2-/- mice having the colitis phenotype, we undertook shotgun metagenomic sequencing analysis of knockout mice." (PMID 32208434, 2020). "Our analyses has elucidated the important features of microbiome dysbiosis and dysfunction in terms of taxa and gene functions in Ap1m2-/- mediated colitis." (PMID 32208434, 2020). "This is the first prospective study using next-generation sequencing method to examine the fecal microbiota composition in Ap1m2+/- and Ap1m2-/- mice and highlights the role of the gut microbiome in the colitis phenotype induced due to the gene knockout." (PMID 32208434, 2020). "Thus beta-lactamase may enhance colitis in Ap1m2-/- mice as well, but the mechanism remains unknown." (PMID 32208434, 2020).
cancer (7 papers, 2016 to 2024). A tumor composed of atypical neoplastic, often pleomorphic cells that invade other tissues. "Dedifferentiation is a hallmark of cancer and it might be anticipated that loss of AP1M2 will prevent proper polarization of cells, thereby contributing to dedifferentiation." (PMID 36672328, 2023). "Furthermore, AP1M2 is linked to immunosuppression in the TME in various cancers." (PMID 38902676, 2024). "A pan-cancer analysis of AP1M2 showed that AP1M2 was abundantly expressed in various cancers, and its expression level was positively correlated with the prognosis of tumor patients." (PMID 36642706, 2023). "The significant tumor SARC (P=0.0023) was selected according to the expression level of AP1M2, and the cancer samples were grouped into high and low expression experimental groups for prognostic KM curves." (PMID 35154321, 2022). "Following the expression levels of AP1M2, cancer cases were categorized into high and low expression groups, between which their correlation between AP1M2 expression and patient prognosis of different cancer types was studied using databases TCGA and GEO." (PMID 35154321, 2022). "AP1M2 was abundantly expressed in a wide range of cancers, and its expression level was positively correlated with the outcome of tumor victims." (PMID 35154321, 2022). "As little research has been made on the correlation between AP1M2 expression levels and tumorigenesis development, this study initiated a pan-cancer analysis of AP1M2 using databases TCGA, GTEx, and CCLE." (PMID 35154321, 2022). "The expression and distribution of AP1M2 gene in tumor tissues and the corresponding normal control tissues were analyzed using the pan-cancer databases GTEx, CCLE, and TCGA." (PMID 35154321, 2022). "Through literature retrieval, little literature on AP1M2 pan-cancer analysis of the overall tumor has been found." (PMID 35154321, 2022). "Several studies indicate that under hypoxia, AP1M2 promotes angiogenesis in different cancer cell lines." (PMID 27070597, 2016). "However, such speculation is inconsistent with gene expression analysis and survival analysis, and more investigations remain indispensable to reveal actions and mechanisms of AP1M2 among a range of cancer types." (PMID 35154321, 2022). "Therefore, AP1M2 may also possess the function of inducing cancer cell death." (PMID 35154321, 2022). "Among other genes in the modules, SH2D3A, AP1M2, CDS1 and SCNN1A haven’t been previously studied in cancer biology." (PMID 28651527, 2017). "As yet, there are no functional studies interrogating the role of AP1M2 in cancer." (PMID 36672328, 2023).
tumor (6 papers, 2019 to 2025). "Subsequently, the association of AP1M2 expression with immune invasion in different tumor types was explored." (PMID 35154321, 2022). "Simultaneously, the investigation of the interrelationship of AP1M2 and tumor neoantigens of the immune system, unstable microsatellite, DNA repair genes, and DNA methyltransferases were explored, and the mutation frequency of AP1M2 gene in diverse tumors was studied." (PMID 35154321, 2022). "By counting the neoantigen quantity of every sample tumor, we subsequently studied whether there was any association with AP1M2 expression." (PMID 35154321, 2022). "Kaplan-Meyer survival plots and proportional hazards model (COX) were employed to evaluate actions of AP1M2 on the clinical prognosis of tumor patients." (PMID 35154321, 2022). "This research currently revealed that AP1M2 expression level in BRCA was positively associated with genetic differences, immune system, DNA methyltransferase, tumor mutational load, and microsatellite instability." (PMID 35154321, 2022). "Meanwhile, the role of AP1M2, possible molecular mechanisms of AP1M2 in different tumor pathogeneses, and clinical outcomes were simultaneously investigated." (PMID 35154321, 2022). "In future research, we plan to use gene editing methods to overexpress or knock out AP1M2 in tumor cells and animal models to verify the function and molecular regulation mechanism of AP1M2." (PMID 35154321, 2022). "The effect of AP1M2 on tumors was analyzed by GSEA, and findings demonstrated that AP1M2 expression levels in most tumors influenced the activation of tumor-associated pathways and immune-associated pathways." (PMID 35154321, 2022). "We investigated the interrelationship of AP1M2 expression levels and the survival prognosis in several types of tumor patients." (PMID 35154321, 2022). "We found that AP1M2 expression could affect survival prognosis, immune infiltration, and tumor load, as well as methylation in tumors, especially BRCA." (PMID 35154321, 2022). "Therefore, based on data from TCGA, CCLE, UCSC Xena, and GTEx databases, as well as gene expression, gene variants, methylation, immune infiltration, and enrichment analysis, a comprehensive exploration was conducted on AP1M2 gene from the 33 different tumor types in the TCGA cohort." (PMID 35154321, 2022). "Hence, the association of increased AP1M2 expression levels with poor prognosis in BRCA patients may be related to the fact that AP1M2 expression suppresses immunocyte infiltration into tumor microenvironment and decreased immune score." (PMID 35154321, 2022). "AP1M2 was identified as upregulated in HBV tumor tissue (logFC = 0.95, p = 0.048) and downregulated in HCV tumor tissue (logFC = −1.92, p = 3.24×10−8)." (PMID 39005337, 2024). "Among the upregulated genes in the tumors compared to those in the normal tissue, we found CKAP4, DUSP1, PAX8, AP1M2, C-KIT and NOTCH3, with NOTCH3 being the only gene that was upregulated in all tumor types." (PMID 31159852, 2019). "The COGS model includes genes such as AP1M2, PLCL1, PLCL2, ITGB3 and BSPRY, whose altered expression could contribute to tumorigenesis and tumor progression." (PMID 40457272, 2025).
AP1M2 also shares sentences with these, for which no sentence is quoted: thyroid cancer (2 papers); bile duct cancer (1); gastric cancer (1); kidney cancer (1); renal carcinoma (1).